NFAT5 (nuclear factor of activated T cells 5)
Diseases named in the same sentence as NFAT5 in open-access papers (continued):
Sharing a sentence is not in itself a finding about the gene and the disease.
autoimmune disease (19 papers, 2013 to 2025). A disorder resulting from loss of function or tissue destruction of an organ or multiple organs, arising from humoral or cellular immune responses of the individual to their own tissue constituents. "Dysregulation of NFAT5 activity is implicated in various pathological conditions, including autoimmune diseases, cancer, and cardiovascular disorders, largely due to its ability to control genes involved in inflammatory and immune pathways under both isotonic and hypertonic conditions." (PMID 40421201, 2025). "In addition to autoimmune diseases, accumulating evidence demonstrates that NFAT5 is associated with the progression of various types of tumors, including breast cancer, hepatocellular carcinoma, and lung cancer." (PMID 30873159, 2019). "Moreover, under isotonic conditions, NFAT5 has been implicated in the pathogenesis of a variety of inflammatory and autoimmune diseases including rheumatoid arthritis." (PMID 30873159, 2019). "Thirdly, NFAT5-downstream osmolyte pathways are potent activators of cytotoxic activities of immune cells and could therefore be implicated in human autoimmune disease." (PMID 30364257, 2018). "The upstream transcription factor NFAT5 is enhanced by the M1-promoting pro-inflammatory and hypoxic conditions associated with autoimmune diseases, which is particularly suggested to regulate the chemokine MCP-1 and subsequent synovial macrophage survival in rheumatoid arthritis." (PMID 30364257, 2018). "NFAT5 plays a pivotal role in both innate and adaptive immunity, making it a key regulator in various autoimmune disorders." (PMID 40421201, 2025). "NFAT5 is known to play a critical role in the high salt-mediated exacerbation of autoimmune diseases along with the induction of inflammatory Th17 CD4+T cell phenotype." (PMID 33918403, 2021). "Numerous studies found that increased expression of NFAT5 was involved in inflammatory and autoimmune diseases." (PMID 34926448, 2021). "Here, we report that the tonicity-responsive enhancer-binding protein (TonEBP or NFAT5), a Rel family protein involved in the pathogenesis of autoimmune disease and inflammation, is required for maturation and function of DCs." (PMID 32499518, 2020). "An essential role has been assigned to NFAT5 in immunity and autoimmune diseases, especially due to its known relevance for macrophage activation and survival, Treg generation, and TH17 differentiation." (PMID 31799221, 2019). "Most recently, NFAT5 has been implicated in the production of TH17 cells, a putative target in the development of autoimmune diseases, via the regulation of Sgk1 expression." (PMID 23618372, 2013). "Targeting NFAT5 could offer new strategies for the treatment of various diseases, including kidney disease, autoimmune diseases, diabetes, blood disorders, cancer and brain diseases." (PMID 40421201, 2025). "This supports the role of NFAT5 in linking osmotic stress with inflammation in autoimmune diseases." (PMID 40421201, 2025). "Collectively, through tonicity-dependent and -independent mechanisms, NFAT5 regulates the development of T1D, another model of autoimmune disease, which seems to be mediated by the induction of AR (under hypertonic conditions) and expansion of Treg cells (under isotonic conditions)." (PMID 30873159, 2019). "Here, we review the essential role of NFAT5 in immunity and autoimmune diseases." (PMID 30873159, 2019). "Taken together, we anticipate that anti-NFAT5 blockades (e.g., small molecules including KRN2 or KRN5 and small hairpin RNAs) will be novel candidates in the treatment of autoimmune diseases such as RA, T1D, and MS in which NFAT5 and its targets play a key role." (PMID 30873159, 2019). "Emerging evidence, however, suggests that NFAT5 might play a more diverse functional role, including a pivotal role in blood pressure regulation and the development of autoimmune diseases." (PMID 23618372, 2013).
autoimmune disease (continued). "Given the pivotal role of NFAT5 in macrophage activation and survival, Treg cell generation, and TH17 differentiation, it is an appropriate therapeutic target for autoimmune diseases." (PMID 30873159, 2019). "Short hairpin RNA (shRNA)-mediated silencing of Nfat5 in CD4 T cells decreased IL-17A and CCR6 expression in Th17 polarizing conditions, suggesting a new role in the pathogenesis of autoimmune diseases involving NFAT5 activation." (PMID 30538703, 2018). "Unlike other calcineurin-dependent NFAT factors, NFAT5 is involved in thymocyte maturation, survival and T-cell proliferation, so the benefit of specific inhibition of NFAT5 for the treatment of autoimmune diseases remains controversial." (PMID 35053254, 2022). "NFAT5 may be a new attractive target for the treatment of autoimmune diseases irrespective of calcium-mediated adverse effects." (PMID 30538703, 2018). "Most recently, it was found that high-salt conditions activate the p38/MAPK pathway involving NFAT5 and SGK1 during cytokine-induced TH17 cell polarization, suggesting that dietary salt may influence autoimmune disease in humans through T-cell-induced production of IL-17." (PMID 25309574, 2014).
hepatocellular carcinoma (19 papers, 2008 to 2025). A malignant tumor that arises from hepatocytes. "PARP1 PARylates NFAT5 and promotes its recruitment to DNA damage sites where NFAT5 prevents R-loop-associated DNA damage in hepatoma cells." (PMID 36909172, 2023). "In hepatitis B virus (HBV) infection, NFAT5 expression is downregulated due to hypermethylation of the AP1-binding site in its promoter within hepatoma cells." (PMID 40421201, 2025). "Compared to normal tissues, the expression of NFAT5 is significantly elevated in hepatocellular carcinoma and lung adenocarcinoma cells." (PMID 40076009, 2025). "We described the involved signaling pathways connecting the NFAT5‐mediated osmo‐adaptive response to the transcriptional maturation of hepatoma and iPSC‐derived HLCs." (PMID 38037844, 2024). "DARS2 promoted cell cycle progression and inhibited hepatocellular carcinoma cell apoptosis via the miR-30e-5p/MAPK/NFAT5 pathway." (PMID 33685397, 2021). "In contrast, NFAT5 promotes apoptosis by inhibiting cell cycle progression in hepatocellular carcinoma and is targeted by microRNAs in RCC which results in poor survival of patients." (PMID 34233711, 2021). "Another study showed that Nfat5 promoted apoptosis and inhibited invasion in hepatocellular carcinoma cell lines." (PMID 32059438, 2020). "In hepatocellular carcinoma, NFAT5 functions as a tumor suppressor and promotes apoptosis with concomitant inhibition of cell cycle progression." (PMID 31756931, 2019). "NFAT5 expression is dramatically elevated in hepatocellular carcinoma and lung adenocarcinoma cells compared with normal tissues." (PMID 30873159, 2019). "We next found that NFAT5 negatively regulated DARS2, and the inhibition of tumorigenesis by NFAT5 on was executed through DARS2 in different hepatoma cell lines." (PMID 29052520, 2017). "The expression of NFAT5 was also significantly downregulated in various hepatoma line cells compared with expression in L02 cells." (PMID 29052520, 2017). "We first found that higher levels of NFAT5 expression predict a good prognosis, suggesting that NFAT5 is a potential tumor-suppressing gene, and verified that NFAT5 promotes hepatoma cell apoptosis and inhibits cell growth in vitro." (PMID 29052520, 2017). "In this study, we investigated the mechanism whereby HBV affects NFAT5 by separating the upstream pathway and convergent downstream pathways of NFAT5 in hepatoma cells." (PMID 29052520, 2017). "We further investigated the mechanism whereby HBV affects NFAT5 through separating the upstream pathway and convergent downstream pathways of NFAT5 in hepatoma cells." (PMID 29052520, 2017). "H89 had been reported to partially inhibit NFAT5 transcriptional activity in the HepG2 hepatocellular carcinoma cell line, and we obtained similar results in T cells." (PMID 18221508, 2008). "On the contrary, NFAT5 acts as a tumor suppressor in hepatocellular carcinoma." (PMID 28983240, 2017). "Second, our results showed that HBV could suppress NFAT5 expression by inducing hypermethylation of the AP1-binding site in the NFAT5 promoter in hepatoma cells." (PMID 29052520, 2017). "Thus, we conclude that HBV downregulates the expression of NFAT5 in hepatoma cells by inducing DNA hypermethylation at the NFAT5 promoter." (PMID 29052520, 2017). "Furthermore, we investigated the effect of NFAT5 on cell cycle and apoptosis in hepatoma cells." (PMID 29052520, 2017). "Our results showed that HBV suppressed NFAT5 expression by inducing hypermethylation of the AP1-binding site in the NFAT5 promoter and inhibiting miR-30e-5p/MAP4K4/DARS2 pathway in hepatoma cells." (PMID 29052520, 2017). "Our results showed that HBV could suppressed NFAT5 expression by inducing hypermethylation of the AP1-binding site in the NFAT5 promoter and inhibiting miR-30e-5p/MAP4K4/DARS2 pathway in hepatoma cells." (PMID 29052520, 2017). "However, in hepatocellular carcinoma (HCC), NFAT5 was identified as a tumor suppressor gene." (PMID 31827081, 2019).
hepatocellular carcinoma (continued). "Hence, we investigated whether the effect of NFAT5 on cell apoptosis and the cell cycle would be hindered by altering DARS2 expression in hepatoma cells to verify our hypothesis." (PMID 29052520, 2017).
melanoma (17 papers, 2012 to 2025). A malignant, usually aggressive tumor composed of atypical, neoplastic melanocytes. "In vivo studies using a C57BL/6 mouse model injected with B16BL6-NFAT5-knockdown melanoma cells demonstrated weak melanoma tumor growth and a decrease in lung and liver nodule formation, further supporting the role of NFAT5 in melanoma growth and metastasis." (PMID 40421201, 2025). "For example, the lncRNA MIAT binds to TCF12 and facilitates its binding to the promoter region of NFAT5 gene, thereby activating NFAT5 expression and promoting melanoma cell proliferation, migration, and invasion." (PMID 39768127, 2024). "For example, NFAT5 promotes T cell proliferation and activation in thymoma and stimulates invasion of melanoma cells." (PMID 34233711, 2021). "NFAT5 expression is regulated by multiple microRNAs, including miR-211 in melanoma; miR-641 in glioma; miR-1b, miR-106a, and miR-363-3p in differentiating Th17 cells; miR-22 in colon cancer; and miR-568 during Treg cells activation." (PMID 31756931, 2019). "Some of the researchers implied it as a tumor suppressor by targeting oncogenic genes such as IGF2R, TGFBR2 and NFAT5 in melanoma." (PMID 28924391, 2017). "Knocking out NFAT5 reduces the invasiveness of melanoma, and the tumor suppressor gene miR-211 is thought to downregulate the expression of NFAT5 in melanoma." (PMID 29052520, 2017). "It has been well documented that miR-211 is a lineage-specific miRNA which is highly expressed in the melanocytic lineage and has been associated with melanoma cell invasiveness via its direct regulation of POU3F2 (BRN2), IGF2R, TGFBR2, NFAT5, and NUAK1." (PMID 25980496, 2015). "The overexpression of lncRNA-MIAT obviously promotes the proliferation, migration and invasion of melanoma cells by regulating the PI3K/AKT signaling pathway and can also strengthen the interaction between TCF12 and the NFAT5 promoter region to promote the progression of melanoma." (PMID 36601121, 2022). "NFAT5 is located at a central node that promotes metastasis in melanoma." (PMID 29052520, 2017). "Mechanistic studies reveal that MIAT enhances NFAT5 transcription by recruiting TCF12 to the NFAT5 promoter, promoting melanoma cell proliferation, migration, and invasion." (PMID 40421201, 2025). "Expression levels of miR-211 are inversely related to melanoma cell migration and invasion, and it has been shown to function as a tumour-suppressor through target genes including IGF2R, TGFBR2 and NFAT5." (PMID 27852308, 2016). "MiR-211 is encoded within the sixth intron of TRPM1, a candidate suppressor of melanoma metastasis, and previous researches demonstrated that overexpression of miR-211 inhibited both anchorage-independent colony formation and invasion, through regulation of IGF2R, TGFBR2, NFAT5 and BRN2." (PMID 23155457, 2012).
diabetes (16 papers, 2013 to 2025). "NFAT5 haploinsufficiency attenuates insulin resistance and suppresses diabetes-associated hepatic steatosis and neuroinflammation." (PMID 33015193, 2020). "Single-nucleotide polymorphisms in the introns of NFAT5 are shown to be correlated with diabetes risk in various human cohorts, and elevated expression of NFAT5 is closely associated with diabetes progression." (PMID 33015193, 2020). "These SNPs are associated with the risk of high blood pressure, diabetes mellitus, diabetic nephropathy, and inflammation, suggesting that genetic variation in NFAT5 transcription might contribute to pathological phenotypes." (PMID 38612478, 2024). "Emerging evidence has shown that its dysregulation results in or is associated with the pathogenesis of diabetes mellitus, which indicates NFAT5 could play a broader role far beyond osmoadaptation in a tissue-specific manner." (PMID 33015193, 2020). "Many patients with diabetes suffer from muscular disorders; one cause of which may be that NFAT5 localization and expression are impaired by elevated levels of proinflammatory cytokine production of these patients." (PMID 33015193, 2020). "The association of AQP1 and NFAT5 co‐expression with aortic stiffness in diabetes and hypercholesterolaemia may represent a novel molecular pathway or therapeutic target." (PMID 31970899, 2020). "Furthermore, NFAT5 deficiency attenuates insulin resistance and reduces macrophage infiltration to adipose tissues in mice with high-fat diet- or streptozotocin-induced diabetes." (PMID 30873159, 2019). "Aberrant NFAT5 levels contribute to several pathologies, including hypoxia, vascular calcification, diabetes, inflammation, chronic kidney disease, bacterial infection, and are seen in breast and lung cancer." (PMID 38612478, 2024). "In this review, we introduce the structure and diverse functions of NFAT5 and its potential as a therapeutic target in diabetes." (PMID 33015193, 2020). "The role of NFAT5 in maintaining cell homeostasis and proliferation is weakened or indeed impaired in diabetes." (PMID 33015193, 2020). "The expression levels of osmotic protective targets of NFAT5 including taurine, betaine, and inositol are lower in patients with diabetes than in healthy people." (PMID 33015193, 2020). "Sensitive molecular sensors such as ROS look promising in counterbalancing the physiological role of NFAT5 in diabetes therapy." (PMID 33015193, 2020). "The percentage of insulin-positive areas was lower in wild-type mice with diabetes mellitus than in NFAT5 haploinsufficiency mice with diabetes mellitus." (PMID 33015193, 2020). "Although several clinical trials have demonstrated the effective role of supplementation with NFAT5 target osmolytes for diabetes treatment, the potential benefit and long-term effects of these drugs are still uncertain." (PMID 33015193, 2020). "Further studies on the crosstalk between NFAT5 and diabetes pathways will give new insights of treatments for diabetes." (PMID 33015193, 2020). "An ideal NFAT5-targeting therapy for diabetes should selectively inhibit inflammatory effects while maintaining the physiological function of NFAT5." (PMID 33015193, 2020). "Overwhelmed adaption of NFAT5 is likely to occur during hyperglycemic crisis in patients with uncontrolled diabetes, particularly during a hyperglycemic hyperosmolar state (HHS), a life-threatening acute metabolic complication." (PMID 33015193, 2020). "The ability of NFAT5 to maintain cell homeostasis and proliferation is impaired in patients with diabetes." (PMID 33015193, 2020). "Rather than exerting a protective effect, upregulation of AR by NFAT5 predominantly aggravates diabetes." (PMID 33015193, 2020). "Here, we describe the current knowledge about NFAT5 and its relationship with diabetes, focusing on its diverse regulatory functions, and highlight the importance of this protein as a potential therapeutic target in patients with diabetes." (PMID 33015193, 2020).